PAK1 (p21 (RAC1) activated kinase 1)
Diseases named in the same sentence as PAK1 in open-access papers (continued):
Sharing a sentence is not in itself a finding about the gene and the disease.
acral melanoma (4 papers, 2022 to 2024). "Subsets of acral melanoma patients harbour amplifications of PAK1 (22% of tumours) and YAP1 (12% of tumours) loci, suggesting a dependency on these pathways for proliferation and/or invasion." (PMID 35159327, 2022). "Identified CNVs in acral melanoma have implicated several genes, including CCND1, CDK4, hTERT, PAK1, GAB2, EP300, YAP1, and MDM2." (PMID 35997352, 2022). "BRAF and NRAS mutations are common in acral melanocytic nevus, whereas acral melanoma shows lower rates of KIT, NF1, BRAF, and NRAS mutations and remarkable copy number variations in genes such as CCND1, CDK4, hTERT, PAK1, and GAB2." (PMID 35997352, 2022). "Amplifications of PAK1 and GAB2 were more commonly observed in acral melanomas, whereas SF3B1 R625 codon mutations were unique to mucosal melanomas (12.9%)." (PMID 35706047, 2022). "Further, PAK1 has been identified as the most recurrently altered kinase gene via fusion events in a smaller cohort of acral melanomas, suggesting that PAK1 may also frequently activate the MAPK pathway outside of BA-SV events." (PMID 38758740, 2024). "PAK1 amplifications were more frequent in acral melanoma (28.6% vs. 11.8%; FDR = 0.041)." (PMID 35706047, 2022).
autism spectrum disorder (4 papers, 2023 to 2025). A spectrum of developmental disorders that includes autism, and Asperger syndrome. "Notably, none of the individuals with the PAK1 variant at the c.1409T position exhibited features of autism spectrum disorder." (PMID 41516310, 2025).
depression (4 papers, 2011 to 2024). "Of relevance to the findings reported here, in a recent study using a rat model of depression, PAK1 gene expression was downregulated in the hippocampus whereas the Rac1 gene was upregulated in the amygdala." (PMID 35592113, 2022). "PAK1 upregulation in hippocampus and cortex is associated with stroke and neurite outgrowth, whereas downregulation of PAK1 has been recently reported in depression." (PMID 22078298, 2011). "Additionally, PAK1 mRNA levels are altered in the prefrontal cortex and hippocampus of depressed subjects, and RT-PCR revealed reduced expression of TGFBR2 in the functional forebrain regions and hippocampus of rodent models of depression." (PMID 39126426, 2024).
Down syndrome (4 papers, 2023 to 2025). "For example, the first data obtained for Down syndrome, the most frequent cause of ID, confirms the hyperactivation of the DsCam/PAK1 module in patient-derived iPSCs and highlight the possibility to target PAKs in this disease." (PMID 36937657, 2023). "In Down syndrome GABAergic neurons, increased Pak1 levels contributed to migration defects through elevated pCofilin." (PMID 40095026, 2025). "Recent findings in iPSC-derived cerebral organoids from patients with Down syndrome showed that inhibiting the DSCAM–PAK1 pathway restored impaired neurogenesis, demonstrating that excessive PAK1 signaling can be targeted with drugs in a neurodevelopmental setting." (PMID 41516310, 2025).
Ewing sarcoma (4 papers, 2020 to 2023). A small round cell tumor that lacks morphologic, immunohistochemical, and electron microscopic evidence of neuroectodermal differentiation. "Also, in the pathogenesis of Ewing Sarcoma, a highly aggressive bone tumour, miR‐130b was reported to induce proliferation, invasion, and migration in vitro and increase metastatic potential via activation of the Cdc42 and Pak1 pathway." (PMID 32860492, 2020).
heart failure (4 papers, 2015 to 2025). Inability of the heart to pump blood at an adequate rate to meet tissue metabolic requirements. "With prolonged stress, Pak1fl/fl hearts demonstrated hypertrophy, whereas the Pak1(cko) hearts progressed and transitioned to heart failure." (PMID 40065530, 2025). "Modulation of Mst1 in Hippo signaling in myocardial I/R injury and heart failure provides salient examples of potential mechanisms by which Pak1 activation may be cardio protective." (PMID 40065530, 2025). "Previous studies had identified Pak1 in the regulation of hypertrophic remodeling that could potentially lead to heart failure." (PMID 25852566, 2015). "They highlight important regulatory functions of Pak1 in Ca2+ homeostasis in cardiac cells, and identify novel potential therapeutic strategies directed at manipulation of Pak1 signaling for the management of cardiac disease, particularly heart failure." (PMID 25852566, 2015).
HIV-1 infection (4 papers, 2013 to 2023). The type species of lentivirus and the etiologic agent of acquired immunodeficiency syndrome (AIDS). "Furthermore, a prior study also revealed that PAK1 depletion strongly inhibited HIV-1 infection in multiple cell systems and decreased levels of integrated provirus, and that overexpression of a constitutively active PAK1 enhanced HIV-1 infection." (PMID 36671485, 2023). "In addition, an RNAi screen identified Pak1 and Pak3 to be important host factors that support HIV-1 infection in HeLa cells and T lymphocytes." (PMID 23622267, 2013). "Furthermore, it has been shown that the depletion of PAK1, and to a lesser extent of PAK3, blocks HIV-1 infection in Jurkat cells." (PMID 36622146, 2023).
inflammatory bowel disease (4 papers, 2020 to 2025). A spectrum of small and large bowel inflammatory diseases of unknown etiology. "Inflammatory bowel disease (IBD) and colitis-associated cancer are associated with activation of PAK1 (p-21 activated kinase 1)." (PMID 40783411, 2025). "Overexpression studies of PAK1, which has been shown to have higher expression in inflammatory bowel disease, showed higher cell proliferation and reduced apoptosis when overexpressed." (PMID 36304467, 2022).
ischemia (4 papers, 2010 to 2023). A hypoperfusion of the BLOOD through an organ or tissue caused by a PATHOLOGIC CONSTRICTION or obstruction of its BLOOD VESSELS, or an absence of BLOOD CIRCULATION. "Isolated mouse ventricular myocytes (VMs) with PAK1 deficiency (PAK1cko) were used to explore PAK1's underlying mechanism on arrhythmic activity during simulated ischemia." (PMID 37122206, 2023). "Depletion of CIB1 in endothelial cells results in decreased PAK1 activation and impaired endothelial cell function, and we have previously reported that CIB1−/− mice exhibit impaired ischemia-induced angiogenesis in retinal and hindlimb tissue concomitant with a decrease in PAK1 activation." (PMID 25379771, 2014). "To assess the contribution of PAK1 to neovascularization, we used both mild and severe forms of HLI that induce ischemia to the muscle tissue supplied by the femoral artery." (PMID 25379771, 2014). "A PAK1 substrate was used to pull down active, GTP-bound Rac1 via its PBD domain, in order to examine Rac1 activity in total CA1 lysates at 3 h following ischemia/reperfusion." (PMID 20830300, 2010). "Previously we found that CIB1, a 22 kDa regulatory protein, plays a critical role in endothelial cell function, angiogenic growth factor-mediated cellular functions, PAK1 activation, MMP-2 expression, and in vivo ischemia-induced angiogenesis." (PMID 20804551, 2010).
neurofibromatosis (4 papers, 2015 to 2020). A hereditary neoplastic syndrome in which tumors grow in the nervous system. "More than 70% of all human cancers, including breast and prostate cancers, RAS-induced pancreatic and colon cancers, and neurofibromatosis-associated tumors, are dependent on PAK1 for their growth and development." (PMID 28098826, 2017).
pancreatic adenocarcinoma (4 papers, 2014 to 2023). "In addition, PAK1 is highly expressed in a proportion of pancreatic adenocarcinoma patients and its expression is significantly associated with MET positivity and linked to a widespread metastatic pattern." (PMID 30971268, 2019). "Moreover, Inhibition of PAK1 by shRNA or pharmacology inhibitor IPA-3 also attenuates cell migration in vitro and tumor metastasis in a model of pancreatic adenocarcinoma." (PMID 30971268, 2019).
prostate tumor (4 papers, 2014 to 2025). "Al‐Azayzih observed that stimulation with TGFβ1 induced prostate tumour cell scattering and increased expression of Snail and N‐cadherin through TRAF6‐mediated activation of Rac1/Pak1 pathway." (PMID 29193723, 2018). "TGFβ1 stimulation induces prostate tumour cell scattering and increases the expression levels of Snail and N‐cadherin through the TRAF6‐mediated activation of Rac1/Pak1 pathway." (PMID 29193723, 2018).
rheumatoid arthritis (4 papers, 2019 to 2024). A chronic, systemic autoimmune disorder characterized by inflammation in the synovial membranes and articular surfaces. "PAK1, a potential mediator of Rac1/Cdc42 signaling pathway, is involved in regulating the migration, invasion, proliferation, and inflammation of fibroblast-like synoviocytes from rheumatoid arthritis patients." (PMID 33482886, 2021).
triple-negative breast carcinoma (4 papers, 2020 to 2023). An invasive breast carcinoma which is negative for expression of estrogen receptor (ER), progesterone receptor (PR), and human epidermal growth factor receptor 2 (HER2). "PAK1 has also been implicated in promoting metastasis in triple-negative breast cancer." (PMID 37190165, 2023).
Ventricular arrhythmia (4 papers, 2013 to 2015). "Here we report a bioactive peptide (PAP) derived from the Pak1 autoinhibitory region increases Pak1 activity, counteracts Ang II-induced pathological hypertrophy in in vitro and in vivo models and associated ventricular arrhythmias in in vivo models." (PMID 25014109, 2014). "Since Ang II is an important mediator in cardiac remodeling and associated ventricular arrhythmias following myocardial infarction, it stimulates the progression of CH and HF, activation of Pak1 may thus represent a novel cardioprotection strategy in these clinical settings." (PMID 25014109, 2014). "In the present study, we explored the effects of a Pak1 bioactive peptide PAP on Ang II induced hypertrophy and associated ventricular arrhythmias in in vitro and in vivo models." (PMID 25014109, 2014). "Our data demonstrate that Pak1 activation by PAP is able to attenuate ventricular hypertrophic remodeling and associated ventricular arrhythmias induced by Ang II." (PMID 25014109, 2014). "We have recently demonstrated that the S1P agonist FTY720 may reduce ischaemia-induced ventricular arrhythmias and SA nodal dysfunction via activation of Pak1, a Ser/Thr kinase downstream of small G-proteins, and Akt." (PMID 23781203, 2013). "We also reported that FTY720 is able to stimulate Pak1 and autophosphorylation and activities in cardiomyocytes, suggesting that FTY720 may be used for the treatment of I/R injury‐induced ventricular arrhythmias." (PMID 25864579, 2015).
acute myeloid leukemia (3 papers, 2022 to 2023). Acute myeloid leukemia (AML) is a group of neoplasms arising from precursor cells committed to the myeloid cell-line differentiation. "Inhibition of PAK1 decreased the bone marrow stromal cells-induced resistance to apoptosis in acute myeloid leukaemia." (PMID 37537668, 2023). "In addition, we found that the expression of PAKs in most tumors was distinctly higher than that in the corresponding normal tissues, while PAK1, PAK2 and PAK4 showed the most significant differences but only in Cholangiocarcinoma (CHOL) and Acute Myeloid Leukemia (LAML)." (PMID 36064705, 2022).
Allergy (3 papers, 2016 to 2022). An allergy is an immune response or reaction to substances that are usually not harmful. "Because PAK1 and eCB are both critically involved in many other organ systems in addition to the brain, our findings may provide a unified mechanism by which PAK1 regulates these systems and their dysfunctions including cancers, inflammations and allergies." (PMID 27296803, 2016). "Several top-ranking genetic perturbagens including PAK1, GSR, RBM15 and TNFRSF12A have been indicated by previous studies to be involved in allergy/asthma." (PMID 35606385, 2022). "As mast cell aggregation in the local tissues plays a critical role in allergy attacks, regulating the expression of Pak1 or using inhibitors to suppress Pak1 activities may be a novel remedy for use in the treatment of allergic diseases." (PMID 35769512, 2022).
Anxiety (3 papers, 2021 to 2023). Intense feelings of nervousness, tension, or panic often arise in response to interpersonal stresses. "Further studies with PAK proteins in mice correlated PAK1, but not PAK5 and PAK6, with anxiety-related phenotypes." (PMID 34125184, 2021).
cervical cancer (3 papers, 2019 to 2022). A primary or metastatic malignant neoplasm involving the cervix. "High PAK1 expression in cervical cancer is associated with its pathological features including angiogenesis, upregulation of MMP2, metastasis and poor prognosis." (PMID 31766427, 2019).
cutaneous T cell lymphoma (3 papers, 2017 to 2020). "The level and the activity of PAK1 are increased in myelodysplastic syndrome (MDS), and a gain in PAK1 gene copy number was found in cutaneous T cell lymphoma (mycosis fungoides/Sezary syndrome)." (PMID 28707321, 2017).
endometriosis (3 papers, 2021 to 2024). The growth of functional endometrial tissue in anatomic sites outside the uterine body. "Researchers have shown that interleukin-1β increases P21-activated inase 1 (Pak1) expression in endometrial stromal cells (ESCs) and that Pak1 immunoreactivity is increased in ovarian cysts in endometriosis." (PMID 38732021, 2024). "Pak1 is a protein, a kinase from the Pak family, which is postulated to be involved in the development of endometriosis." (PMID 38732021, 2024). "Elevated Pak1 expression in endometriosis-afflicted eutopic endometrium implies its potential involvement in the disorder’s initiation and progression." (PMID 38398227, 2024). "Under normal conditions, its level decreases during the secretory phase, but in women with endometriosis, this mechanism may be disturbed, leading to excessive expression of Pak1 in the eutopic endometrium." (PMID 38732021, 2024). "An animal study revealed naringenin potential against endometriosis by reducing expression of various endometriosis prognostic markers (TAK1, PAK1, VEGF, PCNA, MMP2, and MMP-9) in endometriotic lesions developed in rats." (PMID 33919512, 2021).
esophageal squamous cell carcinoma (3 papers, 2013 to 2023). Esophageal squamous cell carcinoma (ESCC) is a type of esophageal carcinoma (EC) that can affect any part of the esophagus, but is usually located in the upper or middle third. "However, the biological function and underlying mechanism of PAK1 in esophageal squamous cell carcinoma (ESCC) remain unclear." (PMID 30971268, 2019). "In esophageal squamous cell carcinoma, pharmacological inhibition of PAK1 reduces cancer cell migration and invasion as well as matrix metalloproteinase (MMP)-2 and MMP-9 expression." (PMID 38188678, 2023). "PAK1 was also reported to be amplified in circulating esophageal squamous cell carcinoma cells." (PMID 24236193, 2013).
fibrosarcoma (3 papers, 2019 to 2020). A malignant mesenchymal fibroblastic neoplasm affecting the soft tissue and bone. "In human fibrosarcoma cells, the expression of PAK1 is reduced and also its phosphorylation (decreased phospho-Ser144 levels) due to transient stimulation." (PMID 33043017, 2020). "We found that PAK1 has both decreased expression and reduced phosphorylation (as shown by phospho-Ser144 levels) when transient stimulation is applied to human fibrosarcoma cells." (PMID 31781560, 2019). "This suggests that having less PAK1 activity is necessary for mechanical stimulation to promote the lengthening of invadopodia in fibrosarcoma." (PMID 31781560, 2019). "In order to determine if PAK1 is involved in the response to mechanical stimulation in human fibrosarcoma cells, it was necessary to examine the total expression level and the level of active PAK1 protein." (PMID 31781560, 2019).
Glucose intolerance (3 papers, 2022 to 2025). Glucose intolerance (GI) can be defined as dysglycemia that comprises both prediabetes and diabetes. "Mice with the most severe glucose intolerance were fed HFD + Dox to induce islet beta cell PAK1 expression." (PMID 39404845, 2025). "Further, beta cell-specific inducible Pak1-KO (βPak1-iKO) mice also exhibit glucose intolerance, beta cell dysfunction and increased beta cell apoptosis." (PMID 39404845, 2025). "We hypothesised that beta cell-specific PAK1 enrichment in vivo can mitigate high-fat-diet (HFD)-induced glucose intolerance by increasing the functional beta cell mass." (PMID 39404845, 2025). "Additional support for developing ways of activating Pak1 therapeutically is in the recent report that enrichment of Pak1 specifically in β‐cells promotes insulin biogenesis and reduces cell death, resulting in suppression of diet‐induced glucose intolerance." (PMID 40065530, 2025). "To evaluate the ability of beta cell PAK1 enrichment to mitigate the negative effects of HFD-induced glucose intolerance and loss of functional beta cell mass in vivo, we used a novel Dox-inducible mouse model to express PAK1 in a beta cell-selective manner." (PMID 39404845, 2025). "Further, we addressed whether beta cell-specific PAK1 induction in vivo could reverse HFD-induced glucose intolerance and hyperglycaemia, and deciphered the mechanisms involved." (PMID 39404845, 2025). "Although whole-body PAK1 knockout mice exhibit glucose intolerance and are insulin resistant, the contribution of skeletal muscle PAK1 in particular was unknown." (PMID 35222279, 2022). "PAK1 plays an unforeseen and beneficial role in beta cells by promoting insulin biogenesis via enhancing the expression of PDX1, NEUROD1 and INS, along with anti-apoptotic effects, that culminate in increased insulin content and beta cell mass in vivo and ameliorate diet-induced glucose intolerance." (PMID 39404845, 2025).
head and neck cancer (3 papers, 2011 to 2025). A primary or metastatic malignant neoplasm affecting the head and neck. "In the study conducted by Park J and his team on head and neck carcinoma cells, it was stated that PAK1 plays a role in tumor cell migration and invasion, and its overexpression correlates with the aggressive behavior of the tumor cell and low survival." (PMID 40864802, 2025). "PAK1 is overexpressed in breast, ovarian, lung and head and neck cancers." (PMID 22848689, 2012).
Huntington disease (3 papers, 2019 to 2023). Huntington disease (HD) is a rare neurodegenerative disorder of the central nervous system characterized by unwanted choreatic movements, behavioral and psychiatric disturbances and dementia. "PAK1-mediated oligomerization of Huntingtin (HTT), which is independent of PAK1 kinase activity, is associated with Huntington’s disease." (PMID 36937657, 2023).
Hyperglycemia (3 papers, 2013 to 2025). An increased concentration of glucose in the blood. "Pak1-knockout (KO) mice fed with a palmitate-rich high-fat diet (HFD) exhibit fasting hyperglycaemia and reduced beta cell mass." (PMID 39404845, 2025). "Furthermore, genes potentially relevant to the pathogenesis of DN were confirmed experimentally, including the cytoskeletal regulator p21-activated kinase 1 (PAK1) and superoxide dismutases (SOD1/SOD2) that catalyse ROS, which accumulates in response to hyperglycemia." (PMID 24575418, 2013).
intestinal cancer (3 papers, 2017 to 2023). "PAK1 knockout resulted in immune system activation to inhibit intestinal tumorigenesis in a mouse model of intestinal cancer." (PMID 37537668, 2023). "Depletion of PAK1 enhanced the immune system and inhibited intestinal tumorigenesis in a mouse model of intestinal cancer." (PMID 36672500, 2023). "The fact that PAK1 expression was positively correlated with the expression of Bmi1 suggests that PAK1 may play a role in the stem cell development and tumorigenesis of intestinal cancers." (PMID 28629331, 2017).